NOTCH3 (notch receptor 3)
Diseases named in the same sentence as NOTCH3 in open-access papers (continued):
Sharing a sentence is not in itself a finding about the gene and the disease.
Hypertension (20 papers, 2015 to 2024). The presence of chronic increased pressure in the systemic arterial system. "In individuals carrying NOTCH3 variants in our cohort, older age, male gender and hypertension were independent risk factors for the conversion of preclinical carriers to symptomatic patients." (PMID 38162905, 2024). "For the 81 subjects carrying NOTCH3 variants, older age and presence of hypertension were independently associated with decreased diffusion tensor image analysis along the perivascular space index." (PMID 38162905, 2024). "While the exact cause of CADASIL remains elusive, studies suggest aberrant NOTCH3 signaling, toxic aggregation of NOTCH3 extracellular domain (NECD), and matrisome alterations influenced by factors like hypertension and smoking." (PMID 38892848, 2024). "We studied both sporadic SVD, for which the major risk factor is hypertension, and also a monogenic form of SVD, CADASIL in which the small vessels are damaged by a different molecular process, namely mutations in the NOTCH3 gene." (PMID 36621823, 2023). "In contrast to our computational results for coronary arteries, previous experiments in pulmonary arteries have shown an increase in Notch3 expression driving arterial thickening in hypertension." (PMID 35839633, 2022). "After NOTCH3 EGFr group, male sex and hypertension were the next most important modifiers of clinical outcomes and neuroimaging markers." (PMID 35862191, 2022). "In our study, we found that disease severity was more strongly determined by NOTCH3 PV position than by hypertension or smoking." (PMID 30032161, 2019). "Moreover, it is interesting that some common NOTCH3 gene SNPs can cause CADASIL and increase the risk of age-related WMH in patients with hypertension." (PMID 35401403, 2022). "NOTCH3 EGFr group is followed in importance by sex, hypertension, diabetes, and smoking." (PMID 35862191, 2022). "Of the overall cohort, 31 patients without hypertension but with white matter disease (Fazekas scale 2 or 3) were selected and genetically analyzed for NOTCH3 gene mutations in the phase 1 cohort (mean age ± SD, 77.4 ± 9.6 11.0; 76.5% men)." (PMID 32477100, 2020). "We analysed four mouse models of SVD (hypertensive BPH mice, Col4a1 mutants, Notch3 mutants and Htra1−/− mice) at different stages for changes in myelin, blood‐brain barrier (BBB) markers, immune cell populations and immune activation." (PMID 39543785, 2024). "In coronary arteries, Notch has been shown to play a critical role in vascular adaptation to hypertension, as demonstrated by a lack of media hypertrophy in Notch3 knockout mice." (PMID 35839633, 2022). "This deficiency has important long‐term implications because mice lacking Notch3 display altered blood pressure increase and develop a severe cardiac and renal phenotype when hypertension is induced chronically." (PMID 35611804, 2022). "Hypertension was significantly more frequent in the SVCI groups (with and without NOTCH3 variants) than in the typical CADASIL group." (PMID 30692550, 2019).
liver fibrosis (20 papers, 2012 to 2026). "miR-571, Notch3 and Jagged1 are up-regulated in patients with liver fibrosis and is associated with the progression of liver fibrosis." (PMID 34750395, 2021). "Finally, silencing of Fam98b inhibited activation of Notch3 and TGFβ/Smad phosphorylation, two pathways implicated in liver fibrosis." (PMID 37919785, 2023). "In liver fibrosis research, ursolic acid can inhibit the expression of Notch3 signaling-related molecules in TGF-β1-activated hepatic stellate cells (HSCs)." (PMID 41602823, 2026). "In vivo experiments have also confirmed that ursolic acid can improve the liver environment in fibrotic mice and inhibit liver fibrosis progression by regulating the Notch3/NOX4 signaling pathway." (PMID 41602823, 2026). "Notch pathway remains a potential target for the treatment of liver fibrosis, but future studies should be directed to Notch 3 signaling and/or targeting different populations of cells." (PMID 39529885, 2024). "Expressions of Notch2, Notch3, and Notch target gene Hes1 were significantly up-regulated during the development of hepatic fibrosis." (PMID 35883205, 2022). "Studies also show that CTD inhibits the differentiation and represses hepatic fibrosis by regulating mitogen-activated protein kinases and Notch3 degradation, respectively." (PMID 33785035, 2021). "Several genes, including NCF and NOTCH3, have been investigated for their roles in the pathogenesis of liver fibrosis." (PMID 34621736, 2021). "PPM1G plays a fundamental role in increasing liver fibrosis by negatively regulating the effect of WWP2 on Notch3 degradation." (PMID 33952716, 2021). "RT-PCR and Western blot were used to detect the expression of Notch3 and Jagged1 in different degrees of liver fibrosis." (PMID 34750395, 2021). "The results of qPCR showed that the expression of Notch3, Jagged1 increased with the progression of hepatic fibrosis and decreased with the reversal of hepatic fibrosis, consistent with previous reports 32-34." (PMID 34239344, 2021). "Inhibition of Notch signaling via γ-secretase inhibitors or NOTCH3-specific shRNA attenuated liver fibrosis progression and HSC activation in several studies." (PMID 31189969, 2019). "In the present study, we show Notch signaling to be highly activated in a rat model of liver fibrosis induced by carbon tetrachloride (CCl4), as indicated by increased expression of Jagged1, Notch3, and Hes1." (PMID 23056328, 2012). "In addition, 3-tigloyl-khasenegasin F, a natural mexicanolide-type limonoid derivative, was found to suppress HSC activation and liver fibrosis through inhibition of the YAP/Notch3 pathway." (PMID 38438584, 2024). "Moreover, CTD represses hepatic fibrosis through the WW domain-containing protein-2-mediated Notch3 degradation and enhances the sensitivity of doxorubicin treatment to chronic myeloid leukemia cells through the PI3K/AKT pathway." (PMID 34299129, 2021). "A total of 74 patients with liver fibrosis in our institution from September to December 2018 were collected for study, and the expression of miR-571, Notch3 and Jagged1 in patients with different progressions of liver fibrosis was determined by RT-PCR and Western blot analysis." (PMID 34750395, 2021). "In the CCl4-induced liver fibrosis rat experiment, qPCR showed that the mRNA expressions of Jagged1, Jagged2, Notch2, Notch3, Notch4 and recombination signal binding protein-κB (RBP-κB) were significantly more upregulated in the CCl4 group than those in the control group." (PMID 34630075, 2021). "The relationship between Notch3 signaling pathway and liver fibrosis has also been deeply studied." (PMID 34750395, 2021). "Although the expression of Notch1 and Notch4 decreased during the progression of hepatic fibrosis, the expression pattern of Hes1, a target gene downstream of Notch signaling, was similar to Notch3 and Jagged1, fluctuated with the progression and regression of hepatic fibrosis." (PMID 34239344, 2021).
liver fibrosis (continued). "In addition, we also observed that lnc-LFAR1 promotes hepatic fibrosis by activating Notch signaling in vitro and in vivo, as demonstrated by an increased expression of the Notch receptors, Notch2 and Notch3, and Notch target gene Hes1." (PMID 28747678, 2017). "The upregulated expression of Notch3 and Hes1 by activated HSCs and the increased synthesis of Jagged1 by neighboring hepatocytes and activated HSCs itself suggest that Notch signaling is activated in rats with liver fibrosis induced by CCl4." (PMID 23056328, 2012). "Consistent with the CCl4-induced rat liver fibrosis model, JY5 decreased the expressions of Jagged1, Notch2, Notch3, Notch4 and RBP-κB in the BDL-induced liver fibrosis model." (PMID 34630075, 2021). "While in CCl4-induced liver fibrosis mice experiment, JY5 not only decreased the mRNA expressions of Jagged1, Notch2, Notch3, Notch4 and RBP-κB, but also downregulated the expression of Dll1." (PMID 34630075, 2021). "In this study, the expressions of Jagged1, Jagged2, Notch2, Notch3, Notch4, and RBP-κB were significantly increased in CCl4-and BDL-induced liver fibrosis in rats and mice." (PMID 34630075, 2021).
prostate carcinoma (20 papers, 2015 to 2025). A carcinoma that arises from epithelial cells of the prostate gland. "Notch3 was shown to be inversely associated with survival in prostate cancer, indicating its increase during cancer progression." (PMID 30555629, 2018). "Notably, the overexpression of Notch1, Notch3 and PlexinD1 induces Slug transcription factor and downregulates E-cadherin levels in prostate cancer cells, a phenotype associated with increased cell migration and metastatic potential in vivo." (PMID 27749937, 2016). "ADT has been shown to increase Notch 3 expression in prostate cancer cells while activation of any of the four NICDs increases resistance to ADT in androgen-dependent prostate cancer cells." (PMID 32575680, 2020). "HES6, though homologous to Notch pathway targets, was unresponsive to NOTCH3–the Notch receptor most highly expressed in prostate cancer cells." (PMID 25864518, 2015). "Module 2 includes COL3A1, COL5A2, and NOTCH3, which have been reported to be associated with metastasis in prostate cancer, as well as HEYL, STMN2, and ASPN, which have been implicated in prostate cancer progression." (PMID 39347576, 2024). "Losses in 1q21.1-21.2 are found significantly more in EOCRC; losses in 11q14.1-14.3 have been associated with aggressive behaviors and familial linkage, albeit in prostate cancers; gains in 19p13.12 may be related with NOTCH3 expression or function." (PMID 30813366, 2019). "In addition, Notch3 is activated by chronic hypoxia, and contributes to the progression of human prostate cancer." (PMID 28416766, 2017). "Notably, overexpression of Notch1, Notch3, or PlexinD1 downregulated E-cadherin levels in prostate cancer cells." (PMID 27749937, 2016). "Notably, both Notch1 and Notch3 expression positively correlates with PlexinD1 levels in prostate cancer, as well as in other tumor types." (PMID 27749937, 2016). "Moreover, both Notch1 and Notch3 induced PlexinD1 expression in two prostate cancer cell lines PC3 and DU145 and in U87MG (data not shown)." (PMID 27749937, 2016). "Additionally, high levels of Notch3 have been described in prostate cancer cells with high metastatic potential." (PMID 26213336, 2015). "Previous studies reported increased Notch3 levels in aggressive prostate cancers 5,6." (PMID 25864518, 2015). "Our results show that Notch3 is the most highly induced Notch receptor in prostate cancer —a finding that suggests this particular receptor may perform an important function in this context." (PMID 25864518, 2015). "However, if RWPE-1 is excluded, Notch3 becomes the second most overexpressed gene in prostate cancer after HES6." (PMID 25864518, 2015). "Compared to their more indolent counterparts, aggressive prostate cancer cells have been reported to up-regulate JAG2, Notch3 and the HES family member HES6 5,6." (PMID 25864518, 2015). "Also, MEF2A can positively regulate neurogenic locus notch homolog protein 3 (NOTCH3), which reduces docetaxel chemosensitivity in prostate cancer." (PMID 40592832, 2025). "Upon NOTCH3 knockdown, levels of HES1 remained steady in 22Rv1 cells but dropped in LnCaP cells, lending further support to the idea that HES1 responds to Notch signalling in prostate cancer cells." (PMID 25864518, 2015). "Notably, as previously shown in prostate cancer cells, A-485 selectively suppressed global acetylation of H3K27, without any significant alteration in global H3K27 tri-methylation status in both Notch1 and Notch3 dependent T-cells." (PMID 31001470, 2019). "Although most of the links between Notch receptors and prostate cancer involve NOTCH1, NOTCH2 was also found increased in several prostate cancer cell lines, with the highest levels expressed in the most aggressive ones, whereas NOTCH3/4 were not detectable." (PMID 35954292, 2022).
CADASIL syndrome (19 papers, 2005 to 2025). "Whereas Notch3 was previously mainly associated with the CADASIL syndrome, our observations in the mouse and a human cohort support a novel role in congenital heart defects and laterality defects." (PMID 40163542, 2025). "Based on the results obtained from the present work, the correlation of Notch3 polymorphisms—mutations with neurodegenerative diseases, especially in CADASIL syndrome—are clearly evident." (PMID 38790158, 2024). "In this review, participants with suspicious clinical CADASIL syndrome and a cysteine-sparing NOTCH3 mutation were selected." (PMID 39201482, 2024). "On the other hand, most mutations in Notch3 lead to neurodegenerative diseases, mainly CADASIL syndrome." (PMID 38790158, 2024). "Patients with NOTCH3 cysteine-sparing mutations manifested with typical clinical CADASIL syndrome and radiological profile, mostly with gait and cognitive impairment but rare WMHs in the anterior temporal pole and external capsule." (PMID 39201482, 2024). "The pathogenic role of cysteine-sparing NOTCH3 mutations with typical clinical CADASIL syndrome is still debated." (PMID 39201482, 2024). "According to MAF and database searching, mutations identified as polymorphisms were also excluded to collect data about potential pathogenic cysteine-sparing NOTCH3 mutations associated with typical clinical CADASIL syndrome." (PMID 39201482, 2024). "Currently, the accumulation of GOMs within the media of the arteries in the skin and the presence of NOTCH3 are the diagnostic hallmarks of CADASIL syndrome." (PMID 36984587, 2023). "Herein, an attempt is made to shed light on the actual molecular mechanism underlying CADASIL syndrome, through insights extracted from comprehensive evolutionary studies and in silico modelling on Notch 3 protein." (PMID 31218211, 2019). "Cysteine-sparing NOTCH3 missense mutations are associated with typical clinical CADASIL syndrome and typical magnetic resonance imaging (MRI) findings, although with less involvement of the anterior temporal lobe." (PMID 28902129, 2017). "Joutel at al identified mutations of the Notch 3 gene, which is located on chromosome 19, responsible for the CADASIL syndrome which presents with WML among other key features." (PMID 20529290, 2010). "CADASIL syndrome is associated with mutations in human Notch3 and is characterized by seizures, late onset neurodegeneration and vascular defects." (PMID 16011804, 2005). "It is currently unknown if these new variants of NOTCH3 associated with cardiac defects behave differently than those observed in patients with CADASIL syndrome." (PMID 40163542, 2025). "Mutations in Notch3 have been directly linked to the CADASIL syndrome." (PMID 38790158, 2024). "Since CADASIL syndrome is a monogenic disease, the opportunity to better interpret the mode of function of Notch proteins and their association with neurodegenerative diseases through mutations occurring in Notch3 was utilized." (PMID 38790158, 2024). "There have been reported to be 310 mutations in Notch3 that cause CADASIL syndrome." (PMID 38790158, 2024). "For example, CADASIL syndrome could be caused by NOTCH3 or HTRA1 mutations, both account for a significant number of SVD and/or ICH patients in our population." (PMID 36580209, 2023). "The pathogenic role of cysteine-sparing NOTCH3 mutations in patients with typical clinical CADASIL syndrome is still unknown." (PMID 31218211, 2019). "The pathogenic role of cysteine-sparing NOTCH3 missense mutations in patients with typical clinical CADASIL syndrome is unknown." (PMID 28902129, 2017). "CADASIL syndrome was diagnosed, with identification of the Notch3 Arg133Cys mutation." (PMID 28003830, 2016). "Association of Notch3 mutations and Notch1 inactivating mutations with CADASIL syndrome and severe heart disorders, respectively, strongly support this hypothesis." (PMID 23531541, 2013).
CADASIL syndrome (continued). "In this systematic review, we conducted a thorough search for cysteine-sparing NOTCH3 missense mutations in patients with typical clinical CADASIL syndrome in order to determine whether these mutations could be considered pathogenic and to describe the patients that carry this type of mutation." (PMID 28902129, 2017). "Gain-of-function of NOTCH3 in CADASIL syndrome is responsible for smooth muscle degeneration in the brain." (PMID 40163542, 2025). "The frequent occurrence of mutations in cysteine residues that are highly conserved in the EGF-like repeats of Notch3 leads to protein misfolding and the manifestation of CADASIL syndrome." (PMID 38790158, 2024). "It is well established that NOTCH3 gene on chromosome 19 is primarily responsible for the development of the CADASIL syndrome." (PMID 31218211, 2019). "In VSMCs, Notch3 has been mostly studied, because of its key implication in the cerebral autosomal dominant arteriopathy with subcortical infarcts and leukoencephalopathy (CADASIL) syndrome in humans." (PMID 23531541, 2013). "Because NOTCH3 p.R544C is the leading hotspot in both familial stroke (15/161, 9.3%, in this study) and sporadic stroke patients in Taiwan, suspicious patients with CADASIL syndrome could be screened for NOTCH3 p.R544C by Sanger sequencing." (PMID 36580209, 2023). "Mutations were considered potentially pathogenic if patients had: (a) typical clinical CADASIL syndrome; (b) diffuse white matter hyperintensities; (c) the 33 NOTCH3 exons analyzed; (d) mutations that were not polymorphisms; and (e) Granular osmiophilic material (GOM) deposits in the skin biopsy." (PMID 28902129, 2017). "Thus, cysteine-sparing NOTCH3 missense mutations are associated with typical clinical CADASIL syndrome and a typical MRI profile, mostly without anterior temporal pole involvement." (PMID 28902129, 2017).
cerebrovascular disease (18 papers, 2019 to 2026). "This study represents the largest population-based analysis of RNF213 and NOTCH3 variants in Koreans and provides valuable insights into the genetic epidemiology of cerebrovascular disorders in Koreans." (PMID 40982447, 2025). "As well as some comorbidities based on cerebrovascular diseases, such as hyperlipidemia, spontaneously hepertensive rats, homocysteineblood syndrome, Notch3 mutation, optically induction, and intracerebral amyloidosis,can be used to prepare VCI model." (PMID 35846430, 2022). "Our findings provide robust evidence from a large population-based study of over 200 000 individuals that common NOTCH3 variants are associated with symptomatic cerebrovascular disease in the general population." (PMID 33712516, 2021). "Based on the severity of the mutation and the known role of NOTCH3 in cerebrovascular disease, we believe that this mutation is most probably the cause of the disease in this family." (PMID 32980981, 2021). "Similarly, understanding the role of Notch in vascular development through Drosophila research has provided insights into CADASIL, a rare cerebrovascular disease caused by NOTCH3 gene mutations." (PMID 38791461, 2024). "Moreover, carriers of CADASIL-susceptible variants may have a higher propensity to develop cerebrovascular diseases, and the distribution of NOTCH3 deleterious variants in the Chinese population differs significantly from what has been reported in the European population." (PMID 37479695, 2023). "However, if the hotspot screening turns negative, it would be tedious and time-consuming to screen the whole NOTCH3 gene by conventional sequencing, or search for other monogenic cerebrovascular diseases." (PMID 36580209, 2023).